LAP3 (leucine aminopeptidase 3)
Diseases named in the same sentence as LAP3 in open-access papers:
LAP3 is named in the same sentence as 45 diseases in open-access papers, as found by Europe PMC text mining. Sharing a sentence is not in itself a finding about the gene and the disease. The quoted sentences say what the papers report.
breast carcinoma (9 papers, 2020 to 2024). "Leucine aminopeptidase 3 in humans (LAP3) is associated with various diseases and cancers, such as breast cancer and ovarian cancer." (PMID 37233473, 2023). "LAP3 is known to play a critical role in breast cancer cells by regulating migration and invasion, and is associated with metastasis." (PMID 36661191, 2023). "In clinical samples of patients with breast cancer, LAP3 was confirmed to be upregulated, while ASS1 was downregulated compared with healthy control." (PMID 35941558, 2022). "LAP3 has been shown to involve in malignant development of human breast cancer cells, thus we wonder if LAP3 also participates in the malignant transformation of BMECs." (PMID 35941558, 2022). "LAP3 is involved in the progression and metastasis of breast cancer by upregulating the expression of fascin and matrix metalloproteinases-2/9 (MMP-2/9)." (PMID 36311709, 2022). "Fang and colleagues just recently showed that LAP3 is involved in migration and invasion of breast cancer cells." (PMID 32717133, 2020). "Lower leucine levels may be due to high expression of leucine aminopeptidase 3 (LAP3) in breast cancer tissues." (PMID 39852119, 2024). "It is well established that LAP3 plays an important role in the metastasis of breast cancer; hence LAP3 inhibitors may have a remarkable effect on the treatment of breast cancer." (PMID 37233473, 2023). "In addition, the immunohistochemical (IHC) showed that positive expression of LAP3 in the breast cancer tissues increased dramatically compared with that in the adjacent tissues." (PMID 35941558, 2022). "Recently, studies have found that LAP3 is involved in the regulation of cell proliferation, angiogenesis, and malignant development of various tumor types including ovarian cancer, glioma, esophageal squamous cell carcinoma, liver cancer, lung cancer and breast cancer." (PMID 35941558, 2022). "LAP3 might be a potential therapeutic target for the treatment of breast cancer." (PMID 35941558, 2022). "Ki16425, a non-lipid competitive inhibitor of LPA1 and LAP3, decreased breast cancer bone metastasis in a mouse model, and Debio0719, the R-stereoisomer of Ki16425, decreased the lung and bone metastasis of breast cancer in a mouse model." (PMID 32674405, 2020).
glioma (5 papers, 2018 to 2023). A benign or malignant brain and spinal cord tumor that arises from glial cells (astrocytes, oligodendrocytes, ependymal cells). "LAP3 is one member of the LAPs and has been reported to be upregulated in diverse cancer types, such as ovarian cancer, glioma, esophageal squamous cell carcinoma and hepatocellular carcinoma." (PMID 35941558, 2022). "Studies have shown that LAP3 is overexpressed in several malignant tumors, including ovarian epithelial malignancy, gliomas, esophageal squamous cell carcinoma, and hepatocellular carcinoma." (PMID 29423100, 2018). "LAP3 is described as being involved in the proliferation, migration, invasion and angiogenesis in various cancers such as ovarian, esophageal, breast, colon and liver cancers as well as glioma." (PMID 35008858, 2021).
hepatocellular carcinoma (5 papers, 2018 to 2023). A malignant tumor that arises from hepatocytes. "Altered LAP3 expression has also been observed in esophageal squamous cell and hepatocellular carcinoma." (PMID 33810334, 2021). "In conclusion, 2D-TPP of the analog compounds PCI-3405 and BRD-3811 and DLPTP analysis revealed their intracellular target space and showed that both bind and inhibit LAP3, a potentially interesting ovarian cancer and hepatocellular carcinoma target." (PMID 33188197, 2020).
colon cancer (4 papers, 2018 to 2021). "In our study, eight proteins including G6PD, GPX3, and LAP3 which are reported to be involved in colon cancer cell growth were connected to glutathione metabolism." (PMID 34386520, 2021). "LAP3 expression was higher in 8 of 8 colon tumor tissues than in matched normal tissue, with mean ER of 6.6 (second row)." (PMID 29423100, 2018). "LAP3 expression was visibly increased in colon cancer tissue when compared with normal colonic mucosa." (PMID 29423100, 2018). "Semi-quantitative assessment of LAP3 expression revealed an average score of 3 for colon cancer tissues and 1.5 for normal colonic mucosa." (PMID 29423100, 2018). "LAP3 expression was present in both normal and colon cancer tissue." (PMID 29423100, 2018). "LAP3 was present in colon cancer cells as well as the surrounding stroma." (PMID 29423100, 2018). "Among the 8 patients tested, all colon cancer tissue displayed strong expression of LAP3." (PMID 29423100, 2018). "A few examples of TAAs identified using proteomics include the markers PSMA1, LAP3, ANXA3, and maspin, which were identified by one group as biomarkers for colon cancer." (PMID 30804938, 2019). "Overall, expression of maspin, ANXA3, LAP3, and PSMA1 was increased in colon cancer tissue extracts." (PMID 29423100, 2018). "Of these, maspin, ANXA3, LAP3, and PSMA1 were reproducibly discovered as serum-reactive in all 3 initially tested cancer samples, including colon tumor tissue from the 2 patients and the liver metastatic tissue from the patient with primary colon cancer and secondary liver metastasis." (PMID 29423100, 2018). "We then used this approach to discover a set of cancer-immunogenic proteins in colon cancer (maspin, ANXA3, LAP3, and PSMA1) and showed that these proteins are overexpressed in the tumor, pointing to a possible abundance mechanism by which these proteins become immunogenic." (PMID 29423100, 2018).
COVID-19 (4 papers, 2021 to 2025). A disease caused by infection with severe acute respiratory syndrome coronavirus 2. "The interferon (IFN)-stimulated 15 KDa protein (ISG15) had the largest increase in serum of COVID-19 patients, followed by several other IFN-induced proteins, such as ILF2, MX1, ISG20, LAP3, and UBE2L6." (PMID 37739942, 2023).
malaria (4 papers, 2009 to 2023). Malaria is a serious and sometimes fatal disease caused by a parasite that commonly infects a certain type of mosquito which feeds on humans. "We have used this technology here to determine a putative interactome of LAP3, an established protein of the crystalloid organelle in malaria parasites, and have included several refinement steps to reduce background." (PMID 32736136, 2020). "In this study, we used LAP3 in the rodent malaria parasite species P. berghei (PBANKA_020450) to carry out a detailed study of crystalloid formation." (PMID 25900212, 2015). "Increased abundance of AIM2 (interferon-inducible and neutrophil-related gene), LAP3 (interferon-inducible gene) and WARS (interferon-response gene) found in our study has also been observed to be over-expressed in patients with malaria." (PMID 19903332, 2009).
mastitis (3 papers, 2023 to 2024). Inflammation of breast tissue during lactation or postpartum due to an obstructed duct or infection. "In conclusion, it first explored genetic variants in the promoter and 5’UTR of the LAP3 gene and uncovered associations between the SNPs and milk production traits as well as clinical mastitis in Sahiwal and Karan Fries cattle." (PMID 37205663, 2023). "Moreover, substantial studies on cattle have reported numerous promising mutations in the LAP3 gene that explain genetic variations in traits such as milk production, somatic cell score, and clinical mastitis in dairy cattle, as well as birth weight in sheep." (PMID 38500063, 2024). "The purpose of this study was to identify genetic variants in the promoter and 5’UTR regions of bovine leucine amino peptidase three (LAP3) gene and analysed their associations with estimated breeding values (EBVs) of milk production traits and clinical mastitis in Sahiwal and Karan Fries cattle." (PMID 37205663, 2023). "Therefore, the current study sought to identify SNPs located in the promoter region of the bovine LAP3 gene and their associations with estimated breeding values (EBVs) of milk production traits and clinical mastitis in Sahiwal and Karan-Fries cattle." (PMID 37205663, 2023). "Our previous studies in dairy cattle unveiled SNP variants in LAP3 and SIRT1 genes that affected the estimated breeding value of milk production traits and clinical mastitis in Sahiwal and Karan Fries dairy cattle." (PMID 38500063, 2024). "Effect of diplotypes of LAP3 gene on the incidence of clinical mastitis in Sahiwal and Karan Fries cattle." (PMID 37205663, 2023). "Chi–square values for mastitis affected and not affected animals with respect to genetic variants of LAP3 gene in Sahiwal and Karan Fries cattle." (PMID 37205663, 2023). "However, studies on the relationship between polymorphisms in bovine LAP3 gene with milk production traits and incidence of clinical mastitis in Sahiwal and Karan Fries cattle are still lacking." (PMID 37205663, 2023). "Altogether, variations in the LAP3 gene promoter could be used as a genetic marker, most notably diplotype H1H3, may greatly benefit the simultaneous improvement of mastitis resistance and milk yield traits in dairy cattle." (PMID 37205663, 2023).
Non-Alcoholic Fatty Liver Disease (3 papers, 2023 to 2025). "Further, we observed an increased expression of LAP3 (involved in glutathione metabolism), a target that has previously found to be positively correlated with fasting blood glucose levels and has, by inhibiting autophagy, been implicated in the progression of Non-Alcoholic Fatty Liver Disease." (PMID 36930661, 2023). "An in vivo study indicated an upregulated LAP3 expression in the hepatocytes and serum of rats fed a high-fat diet, which induces non-alcoholic fatty liver disease (NAFLD) and inhibits autophagy in LO2 cells." (PMID 40836955, 2025).
colorectal cancer (2 papers, 2018 to 2022). A primary or metastatic malignant neoplasm that affects the colon or rectum. "MMP-2/9 is a member of the MMPs family that is highly expressed in colorectal cancer, gastric cancer, and nasopharyngeal carcinoma and closely related to tumor invasion and fibrosis, and knockdown of LAP3 can reduce MMP-2/9 expression and consequently cell invasion." (PMID 36311709, 2022).
liver cancer (2 papers, 2020 to 2021). An epithelial or non-epithelial malignant neoplasm that arises from the liver. "Application of DLPTP to 2D-TPP datasets profiling the HDAC8 inhibitor PCI-34051 and its analog BRD-3811 let us discover that both compounds inhibit LAP3, an interesting ovarian and liver cancer target." (PMID 33188197, 2020).
multiple myeloma (2 papers, 2020 to 2021). "Melflufen could be hydrolyzed to its active form by the aminopeptidases LAP3, LTA4H, RNPEP, and ANPEP, all of which are expressed in multiple myeloma." (PMID 33810334, 2021).
cerebrovascular diseases (1 paper, 2022). "LAP3 (leucine aminopeptidase 3) has been reported to play a vital role in the pathogenesis of nonalcoholic fatty liver disease (NAFLD), which is a known risk factor for T2DM and is associated with cardiovascular and cerebrovascular diseases." (PMID 35955709, 2022).
colon adenocarcinoma (1 paper, 2018). "We first examined the differential expression levels of maspin, ANXA3, LAP3, and PSMA1 in normal colonic mucosa vs. colon adenocarcinoma by 1D Western blotting." (PMID 29423100, 2018).
diabetes (1 paper, 2011). "Only Hspa1b and Lap3, which were determined to be up-regulated with diabetes by both DIGE and iTRAQ, were observed by multiple methods." (PMID 21249158, 2011).
Granuloma (1 paper, 2024). A compact, organized collection of mature mononuclear phagocytes, which may be but is not necessarily accompanied by accessory features such as necrosis. "Therefore, the upregulated expression of LAP3 in the lung tissue and blood samples may be closely related to angiogenesis in the granulomas of patients with PTB and the level of inflammation induced by tuberculosis." (PMID 39023413, 2024). "Similar to TYMP and LAP3, the upregulated expression of ANXA3 in the blood samples may be closely related to angiogenesis in the granulomas of patients with PTB." (PMID 39023413, 2024).
Hyperglycemia (1 paper, 2023). An increased concentration of glucose in the blood. "BeWo cytotrophoblasts exposed to hyperglycemia displayed increased mRNA expression of ACSL1, HSD11B2, RPS6KA5, and LAP3 and reduced mRNA expression of CYP2F1, and HK2, concomitant with increased levels of: lactate, malonate, and riboflavin metabolites." (PMID 36930661, 2023).
liver diseases (1 paper, 2022). "Emerging studies have reported that LAP3 was involved in different liver diseases." (PMID 35404840, 2022).
psoriasis (1 paper, 2015). An autoimmune condition characterized by red, well-delineated plaques with silvery scales that are usually on the extensor surfaces and scalp. "All other DEGPs could be placed along a continuum, with some showing greater psoriasis specificity (e.g., DBI, GLTP, HRNR, KRT73, ELOVL7), and others showing similar expression shifts in many or most skin diseases (e.g., MX1, S100A8, S100A9, STAT1, LAP3)." (PMID 26251673, 2015).
tuberculosis (1 paper, 2024). A chronic, recurrent infection caused by the bacterium Mycobacterium tuberculosis. "For example, a panel of markers, such as TYMP, LAP3, ANXA, and SULF1, along with traditional tuberculosis‐related symptoms such as persistent cough, weight loss, and fever, can be used to differentiate between patients with cancer, post‐SARS‐CoV‐2 infection, and those at risk for tuberculosis." (PMID 39023413, 2024). "The results of ROC showed that TYMP (AUC = 0.964), LAP3 (AUC = 0.914), ADGRL2 (AUC = 0.98), SIL1 (AUC = 0.936), LMO7 (AUC = 0.856), SULF1 (AUC = 0.96), ANXA3 (AUC = 0.798), and PACSIN3 (AUC = 0.747) had high accuracy in predicting tuberculosis." (PMID 39023413, 2024).
uveitis (1 paper, 2021). An inflammatory process affecting a part of or the entire uvea. "In a pilot study on three children with JIA-uveitis, elevated levels of proteins associated with inflammatory arthritis (SEMA3G, TIMP1, HEXB, ERN1, and SAA1) was found, in addition to elevated levels of sCD14, S100A8, and SAA1, but reduced levels of S100A9, LAP3, TTR, and MIF." (PMID 34438537, 2021).
vitiligo (1 paper, 2025). Generalized well circumscribed patches of leukoderma that are generally distributed over symmetric body locations and is due to autoimmune destruction of melanocytes. "This analysis identified four genes—STAT1, VAMP5, LAP3, and TYMP—that exhibited both strong module membership and significant upregulation in vitiligo." (PMID 41498037, 2025).
tumor (14 papers, 2017 to 2026). "To test whether LAP3 plays a causal role in tumor behavior, we established stable LAP3-overexpressing A549 and PC9 cell lines, confirming robust upregulation at both mRNA and protein levels." (PMID 41836418, 2026). "In cancer, LAP3 has also been linked to tumor cell proliferation, migration, and invasion." (PMID 33810334, 2021). "Leucine aminopeptidase 3 (LAP3), a key member of the LAP family, is closely linked to tumor cell proliferation, migration, and malignancy grade." (PMID 40836955, 2025). "LAP3, ADRA1D, KIF25, GPS2, and MCF2L genes were associated with proliferation, movement, and invasion of tumor cells." (PMID 39839768, 2024). "Results of tissue microarray IHC further certificated GBP1, BIN2 and LAP3 were overexpressed in EBVaGC tumour tissues." (PMID 36519208, 2023). "Previous studies have reported that LAP3 exerted harmful roles in the pathogenesis and progression of many tumor diseases." (PMID 35404840, 2022). "LAP3, one of the important M1 members of LAPs, serves multifunctional roles in tumor metastasis, such as promoted cell proliferation and migration in glioma tumors, advanced malignant development of human ESCC." (PMID 35404840, 2022). "Notably, LAP3 was selectively enriched in both tumor epithelium and a distinct macrophage subset." (PMID 41836418, 2026). "Although LAP3 (ranked six in predictor importance) represented the most distinct case in this analysis, it showed a positive expression (count > 0) in approximately 20% to 65% of malignant cells in the individual tumors, suggesting potential tumor heterogeneity." (PMID 41212151, 2025). "Functionally, LAP3 facilitates immune evasion through impaired CD8+ T cell infiltration and cytotoxicity in the GC tumor microenvironment (TME)." (PMID 41748538, 2026).
cancer (11 papers, 2018 to 2024). A tumor composed of atypical neoplastic, often pleomorphic cells that invade other tissues. "Studies have shown that LAP3 is also involved in the angiogenesis of various cancers, and has a potential role in regulating inflammation." (PMID 39023413, 2024). "Their experiment described differential expression of proteasome subunit alpha type 1 (PSA1), leucine aminopeptidase 3 (LAP3), annexin A3 (ANXA3), and maspin (serpin B5), demonstrating a proteomic profile of antibody-inducing cancer-associated immunogens." (PMID 31828035, 2019). "The current functional studies on LAP3 expression mainly focus on the field of cancer." (PMID 36011349, 2022).
infection (6 papers, 2013 to 2024). The state of being infected such as from the introduction of a foreign agent such as serum, vaccine, antigenic substance or organism. "The transcription level of most genes involved in GSH metabolism, including Gpx1, Ggt1, Gsr, Pgd, Anpep and Lap3, was significantly higher post-infection than pre-infection in the delta group but not in the omicron group." (PMID 39759510, 2024).
LAP3 also shares sentences with these, for which no sentence is quoted: ovarian carcinoma (4 papers); esophageal squamous cell carcinoma (3); gastric cancer (2); atrial fibrillation (1); Azoospermia (1); bacterial infection (1); bacterial vaginosis (1); brain tumours (1); central nervous system disorder (1); esophageal cancer (1); glioblastoma (1); Hypertension (1); immune system disorder (1); infectious disease (1); lung carcinoma (1); nasopharyngeal carcinoma (1); Obesity (1); trichomonas vaginitis (1); upper respiratory tract infection (1); vaginitis (1); yellow fever (1).